CASP8 (caspase 8)
Diseases named in the same sentence as CASP8 in open-access papers (continued):
Sharing a sentence is not in itself a finding about the gene and the disease.
cancer (continued). "The dysfunction of caspase-8 may contribute to malignant tumor development in mice and humans." (PMID 38572238, 2024). "The cell response to Caspase 8 and Caspase 9 expression pattern at higher doses of MuSCF-NPs, can be attributed to the cancer cell compensatory mechanisms and anti-apoptotic gene-regulators recovering process, which lead to the drug-resistant potential of cancer cells." (PMID 38600497, 2024). "Caspase-8 phosphorylation has been investigated over the past twenty years as one of the mechanisms responsible for Caspase-8 enzymatic inactivation, promoting in contrast the acquisition of new protein functions critical for cancer development and sustainment." (PMID 37444381, 2023). "Importantly, given the increase in cancer-related functions specific for Caspase-8, we hypothesize Caspase-8 may influence cancer progression by also impacting on cell cycle checkpoints." (PMID 37444381, 2023). "Depending on cancer type, the expression of Caspase-8 may be up- or downregulated." (PMID 37444381, 2023). "In addition, it will be interesting to investigate whether the expression and activity of tyrosine phosphatases may impinge on Tyr380 phosphorylation and contribute to modulating Caspase-8 activity and function in cancer." (PMID 37444381, 2023). "The molecular mechanisms that may modulate the function and the activity of Caspase-8 in cancer are still largely obscure; however, the interplay between Caspase-8 and the aberrant tyrosine phosphorylation signaling that characterizes most tumors is emerging as a major character." (PMID 37444381, 2023). "Eight targets (EP300, CASP3, CASP8, CHEK2, CREBBP, NOTCH1, PPARG, and TGFBR2) were TSGs (gray text), suggesting that antagonizing these molecules might increase the susceptibility to cancer in healthy individuals." (PMID 37888486, 2023). "Consequently, the Th-nanoemulsion has a potential anticancer effect as it reduces the growth and proliferation of HepG2 and MCF-7 cancer cells, increases apoptosis by increasing casp-8 and casp-9 activities, and finally lowers the level of VEGFR-2 concentrations." (PMID 37836753, 2023). "In addition to its traditional function of initiating cell death, Caspase-8 is also implicated in several non-apoptotic processes in various cancers, including cell-cycle control, proliferation, migration, invasion, and angiogenesis." (PMID 36399280, 2022). "In our research, we found that the deletion of Casp8 in NK cells resulted in the dysfunction of the NK cells, but it also increased the expression of PD‐1 and CTLA‐4 on NK cytomembranes, which has been reported to be associated with poor prognosis in various cancers." (PMID 33934451, 2021). "While analyzing multiple cancer disorders, we found highly variable expression among genes implicated in cancer: EEF1A1, GNAS, NPM1, PIM1, and RHOA are known oncogenes; H3F3A, PTPRC, SMARCB1, and B2M are possible oncogenes; and CASP8, JAK1, and PRKAR1A are known tumor suppressor genes." (PMID 34174938, 2021). "We hypothesized that low Caspase 8 function reduces the ability of cancer cells to undergo apoptosis when exposed to standard chemotherapy and that second mitochondria-derived activator of caspases (Smac)-mimetics could increase cell death in combination with chemotherapy." (PMID 34088893, 2021). "Using multiple tools such as differential gene expression, gene set enrichment, gene ontology, in silico immune cell estimates, and survival analyses to mine data in The Cancer Genome Atlas, we compared the molecular features and survival of these carcinomas with and without CASP8 mutations." (PMID 30775178, 2019). "With this in mind, Caspase 8 may also affect cancer cell metastatic potential and behavior." (PMID 31475104, 2019). "Furthermore, the present results indicated that the high percentage of neurons containing GAL and low percentage of CASP-8 in the MPs of cancer-affected stomach wall might also reflects neuroprotective role of this peptide." (PMID 30019295, 2018).
cancer (continued). "Interestingly, although Capan-2 cell line appeared unaffected in terms of cell cycle arrest at 24 h; yet, the cleaved bands for caspase 8 and 3 were seen in Capan-2 treated cells too, which suggested that rfhSP-D can affect the cancer cells via multiple pathways." (PMID 29915574, 2018). "Immunocytochemistry method was used to investigate apoptosis as possible mechanism for inducing cancer cells viability reduction by fractions G, I, and J. The results showed that fraction G, I, J, and Sarcophine induced apoptosis in cancer cells by expression of caspoase-3 and caspase-8." (PMID 29881421, 2018). "RTK-driven Y380 phosphorylation of caspase-8 might prime certain cancer cells to become unresponsive to the apoptotic signal triggered by cytotoxic CD95L, thereby diverting this cell signaling pathway toward promoting cell migration, an essential step in cancer cell metastasis." (PMID 29021794, 2017). "However these insights were not entirely conclusive, since some other studies failed to confirm a significant cancer protective effect of these caspase 8 variants." (PMID 27507139, 2016). "Previous studies showed that MALAT-1 promotes cancer progression, mainly through the regulation of gene expression, for example, the epithelial mesenchymal transition associated genes, ZEB1, ZEB2, and Slug and the apoptosis related genes, CASP3, CASP8, BAX, BCL2, and BCL2L1." (PMID 26989678, 2016). "Our approach is a proof-of-concept strategy leading to the discovery of a novel small molecule that not only stimulates TRAIL-induced apoptosis in cancer cells, but may also provide insights into the structure-function relationship of caspase 8 homodimers as putative targets in cancer." (PMID 25962125, 2015). "More importantly 9 new cancer genes were identified; seven of them (ARID1B, CASP8, MAP3K1, MAP3K13, NCOR1, SMARCD1, CDKN1B) carried truncating mutations and were characterized by biallelic inactivation, suggesting that they were potentially recessive cancer susceptibility genes." (PMID 26561834, 2015). "However, the cleaved-caspase-8 was almost undetectable in both cancer cells." (PMID 23840452, 2013). "Growing evidences, including meta-analysis about extrinsic initiator CASP8, have suggested that some CASP polymorphisms may deregulated the expression and activity of caspase and have attempted to correlate CASP polymorphisms with cancer risks." (PMID 22616010, 2012). "Moreover, Caspase 8 is silenced by methylation in several other classes of cancer." (PMID 21712824, 2011). "In particular, CASP8 and NLRP3 were hypomethylated in many cancers, whereas RIPK3 was hypermethylated." (PMID 38436818, 2025). "Specifically, for GBM (adults) and GBM_DE (children), four genes (CASP8, PIK3CA, PTEN, LPAR4) related to pathways in cancer are identified." (PMID 40768543, 2025). "For PFS, biomarkers were detected in 10 cancer types, with CALR, CASP8, FOXP3, and LY96 consistently identified in at least three cancers." (PMID 41150760, 2025). "The inhibition of c-FLIP interactions with the FADD precludes c-FLIP from its recruitment into the DISC, and allows caspase-8’s binding to the FADD, promoting TRAIL-induced apoptosis in resistant cancer cells." (PMID 38248348, 2024).
cancer (continued). "Therefore, we investigated the evolutionary history of cancer associated gene sequences across 384 mammalian taxa, to detect signatures of selection across categories of oncogenes (GRB2, FGL2 and CDC42), tumour suppressors (LITAF, Casp8 and BRCA2) and immune genes (IL2, CD274 and B2M)." (PMID 38773187, 2024). "In contrast, the biomarkers uPA, IL-18R1, EN-RAGE, CASP-8, MCP-2, TNFβ, CD5 and CXCL10, whose functions are related to cancer or inflammatory processes, had their expression inhibited." (PMID 39247198, 2024). "Moreover, analyses that predict the relationship between caspase-8 expression and patient survival outcomes suggest that high levels of caspase-8 may correlate with either a poor or favorable prognosis, depending on the type of cancer." (PMID 39625520, 2024). "An OCSCC cohort more than twice the size of the TCGA cohort allowed us to find additional cancer driver genes that are frequently affected in CNA-quiet OCSCC, notably PIK3CA, RAC1, and TERT, besides the previously established HRAS and CASP8." (PMID 39428388, 2024). "However, the results obtained in this study suggest that PRMT5 can also promote apoptosis via methylation of caspase-8, which may also be important for breaking the resistance of cancer cells and must be taken into account in the design of therapies targeting the methylation networks of the cell." (PMID 38730267, 2024). "In cancer cells, TRAIL exerts its apoptotic effects through activation of caspase 8, which triggers apoptosis cascade by binding to the death receptors TRAIL-R1 and TRAIL-R2 on target cancer cells." (PMID 37958844, 2023). "At the molecular level, RT-qPCR was used to assess gene expression of CASP8, TNF-α, and IL-6 genes in Caco-2 and COLO-205 cancer cells." (PMID 36770882, 2023). "Curcumin can also exert its anti-cancer properties by regulating cyclin D, CASP8 (caspase-8), and inhibiting NF-κB (nuclear factor κB) secretion." (PMID 37107631, 2023). "Together, our results support a role for ERK5 kinase activity in conferring resistance to TRAIL-induced apoptosis in cancer cells, whereas ERK5 inhibition improves TRAIL anticancer activity by favoring caspase-8 activation." (PMID 37919293, 2023). "Furthermore, we queried twenty cancer databases from The Cancer Genome Atlas (TCGA) with overall survival data to determine whether the impact of Caspase-8 expression was a significant predictor of improved or worsened overall survival by Kaplan–Meier analysis." (PMID 37444381, 2023). "The results showed that MLKL had a strong positive correlation with CASP8, ZBP1, FASLG, RIPK1, and RIPK3 in all 33 cancer types, and RIPK3 was also strongly correlated with CASP8, MLKL, and ZBP1." (PMID 37000317, 2023). "In line with this, we can therefore speculate that the rewiring of Caspase-8 function in cancer may be a direct consequence of the ability of constitutively active RTKs to promote the hyperactivation of Src family tyrosine kinases and therefore drive Caspase-8 phosphorylation on Tyr380." (PMID 37444381, 2023). "Collectively, this study links metabolites with the pyroptosis pathway and illustrates how α-KG triggers DR6 endocytosis to bring about caspase-8/GSDMC-mediated pyroptosis, and thus, has application in cancer therapy." (PMID 35673561, 2022). "The biomarkers caspase-3, caspase-8 and HSP27 were measured in plasma at inclusion of 4,284 study participants aged 46–68 years in the population-based Malmö Diet and Cancer study (MDCS)." (PMID 35310100, 2022).
cancer (continued). "Although in different cancer settings, previous studies reported inhibition of p38 MAPK-triggered apoptosis via activation of caspase-8 and/or caspase-9." (PMID 35681235, 2022). "It is noteworthy that nuclear programmed death ligand 1 (nPD-L1) can upregulate GSDMC, whereas TNF-α-activated caspase-8 can cleave GSDMC, which will switch apoptosis to pyroptosis in cancer cells." (PMID 35962439, 2022). "Among these signatures (TNF, TIRAP, CASP9, PLCG1, PRKACA, CASP3, CASP8, CASP4), TNF (Tumor necrosis factor) is currently considered a two-edged sword in cancer development." (PMID 35741587, 2022). "In contrast, the T3 isomers (α-, γ-, and γ-T3) predominantly activate proteins involved in apoptotic signaling, such as Bax, Bid, Caspase-3, Caspase-8, cytochrome c, and TRAIL, while suppressing the Bcl-2 ratio, which is reported in various cancers." (PMID 35889829, 2022). "Experiments showed that cancer cells depleted of UHRF1 would activate the DNA damage response pathway, resulting in cell cycle stagnation in G2M and apoptosis dependent on the caspase-8 pathway." (PMID 35656341, 2022). "Significantly upregulated PRGs included PYCARD in 12 cancers; GSDMB in 10 cancers; IL18 in 9 cancers; GSDMD, CASP8, GZMB, and GPX4 in 8 cancers; AIM2 and CASP6 in 7 cancers; GZMA in 6 cancers; GSDME, CASP4 and DHX9 in 5 cancers; GSDMA and GSDMC in 4 cancers." (PMID 36605187, 2022). "Studies in cancer cell lines demonstrated that the intracellular accumulation of TRAIL receptor-2 (TRAIL-R2) and the subsequent activation of caspase-8 contribute significantly to apoptosis induction upon ER stress." (PMID 35075141, 2022). "In other reports, nitric oxide donors have been shown to induce cancer cell death by upregulating the expression of RASSF1 and CDKN1A, activating caspase 8/3 and regulating anti-apoptotic BCL-2 family members." (PMID 35205790, 2022). "It enhanced apoptotic cell death in cancer cells through ROS-dependent and -independent AIF release or caspase 8 activation and bax translocation." (PMID 35309511, 2022). "Previous studies reported that anti-cancer agents (e.g., MLN4924) transcriptionally activated ATF4 by inducing ER stress, and subsequently induced CHOP-mediated DR5 transcription and caspase 8-mediated extrinsic apoptosis." (PMID 35754502, 2022). "IRAK2 silencing also decreased the expression of cleaved caspase-8 and -3 in both two types of OSCC cancer cells when compared with their control cells." (PMID 34249686, 2021). "We have also shown a significant increase in cleaved caspase-8 suggesting activation of extrinsic pathway of apoptosis in SO-treated HeLa and MCF7 cancer cells." (PMID 33953846, 2021). "Treatment with B. adolescentis significantly up-regulated the expression level of caspase-8, Fas-R, and BAD genes in HT-29 and Caco-2 cancer cell lines." (PMID 33980239, 2021). "In cancer cells only, TLR3 acquires death receptor properties by efficiently triggering the extrinsic pathway of apoptosis with Caspase-8 as apical protease." (PMID 34011952, 2021). "In the present study, the investigation of underlying mechanisms revealed that the B. adolescentis is able to trigger apoptosis by upregulation of caspase-8, Fas-R, and BAD gene expression in HT-29 and, Caco-2 cancer cell lines." (PMID 33980239, 2021). "In numerous studies on cancer cell lines, it has been shown that death receptor 5 (designated DR5, or TRAIL-R2) and caspase-8 play an essential role in Tg-induced apoptosis via UPR (in a response to ER stress)." (PMID 33374919, 2020). "Precaution should be taken when using NDGA as anti-cancer agent, considering that, in particular types of cancer such as malignant glioma, NDGA can inhibit caspase 8 and 3, poly(ADP-ribose)polymerase cleavage and consequent CD95L-mediated apoptosis." (PMID 32184727, 2020).
cancer (continued). "It was also found that treatment of cancer cells with a caspase-8 inhibitor significantly suppressed C5-induced apoptosis; however, treatment with caspase-9 inhibitors did not affect C5-induced apoptosis, suggesting that C5 may induce apoptosis via the extrinsic pathway by activating caspase-8." (PMID 32075108, 2020). "In summary, the data suggest that the increased cancer stemness seen in cells stimulated through CD95 is dependent on the expression of the two main DISC components FADD and caspase-8." (PMID 31992798, 2020). "It was shown that TRAIL-triggered cytokine secretion from TRAIL resistant cancer cells is FADD- and caspase-8 dependent." (PMID 31010082, 2019). "Taken together, these results indicate that single inhibition of either cIAPs or c-FLIP can sensitize cancer cells to TLR3-mediated, RIPK1/caspase-8-dependent apoptosis." (PMID 30158588, 2018). "Triple-immunofluorescent staining revealed significantly higher percentage of CASP8 and PGP 9.5 stained neurons in plexuses located distally from the tumor when compared to the cancer-affected stomach wall." (PMID 30019295, 2018). "Moreover, under non-apoptotic conditions, such as Caspase-3 deficiency, Caspase-8 may stimulate cancer cell migration and metastatization by enhancing Calpain activity, by interacting with focal adhesion and with Rab5." (PMID 30501030, 2018). "Expression of caspase-8 and caspase-3 in MDA-MB-231 cancer cells treated by fractions G, I, and J increased which the results were comparable with Sarcophine." (PMID 29881421, 2018). "The top three non-cancer disease genes regulated by the co-functional module and mapped to the pathways are MMP2, VEGFA and CASP8, while for the cancers are BCL2, MDM2 and VEGFA." (PMID 28340554, 2017). "Impaired caspase 8 function reduces T lymphocyte “activation-induced cell death” (AICD) activity, which is important in immune surveillance of cancer cells." (PMID 28915630, 2017). "A computational study was carried out on cancer-related targets including IL-2, IL-6, COX-2 Caspase-3 and Caspase-8." (PMID 28344831, 2017). "For the three non-cancer diseases related genes (MMP2, VEGFA and CASP8), the percentage is just around 30%." (PMID 28340554, 2017). "Here in our results, the active caspase-9, caspase-8, caspase-3, and PARP, were remarkably increased by AZOX in KYSE-150 cells, indicating that the apoptosis pathway is one of the anti-cancer mechanisms of AZOX." (PMID 28567017, 2017). "The current study has demonstrated that S1P-dependent TRAF2 polyubiquitination, downstream of caspase-8, is important for mediating DR5 suppression-induced promotion of cancer cell invasion." (PMID 28482915, 2017). "Our data indicate that ML327 sensitizes carcinoma cells to TRAIL as evident by increases in PARP cleavage, caspase 8 cleavage, caspase 3/7 activation, Annexin V binding to PS residues, and Sub G0 cell population after ML327 pre-treatment." (PMID 29254146, 2017). "The present findings also show that treatment with A. marina leaf extracts and fractions leads to activation of PARP, caspase 3, and caspase 8 in AU565, BT483, and HepG2 cancer cell lines." (PMID 27078842, 2016). "The regulation of DISC-engaged molecules, including c-FLIP and caspase-8, has been observed to contribute to the sensitivity of TRAIL-mediated apoptosis in cancer cells." (PMID 25333816, 2015). "The extrinsic pathway of the apoptosis of human cancer cell lines MCF-7 and MDA-MB-231 after the SAMC treatment was revealed by the increase of FADD (fas) and the activation of caspase-8." (PMID 25070343, 2014). "Western blot analysis also demonstrated that TCN significantly induced the activation of caspase-8 and caspase-3, as well as the cleavage of PARP-1 in the four cancer cell lines." (PMID 23936501, 2013).